TNF (tumor necrosis factor)
Diseases named in the same sentence as TNF in open-access papers (continued):
Sharing a sentence is not in itself a finding about the gene and the disease.
malaria (continued). "In contrast we observed a negative correlation between the relative proportion of malaria-specific nnCD4+ T cells producing TNFα and parasite prevalence (Rs = −0.35, p = 0.023 [spearman correlation]), although this did not remain not significant on multivariable analysis." (PMID 37634385, 2023). "Also, although IL-10 was not in any of the four patterns for malaria, there was a positive correlation between IL-10 and TNFα levels." (PMID 35811678, 2022). "Whole blood from asymptomatic participants with and without positive malaria microscopy were ex-vivo stimulated with S. aureus, E. coli LPS and Salmonella Typhimurium; cytokine concentrations (TNF-α, IFN-γ, IL-1β, IL-6, IL-10) were measured on supernatants using ELISA." (PMID 34177883, 2021). "Participants with asymptomatic malaria had also lower IFN-γ and IL-10 responses after Salmonella Typhimurium stimulation, while monocyte cytokines (IL-1β, IL-6, TNF-α) were not statistically different between slide negative participants and participants with asymptomatic malaria." (PMID 34177883, 2021). "We evaluated the expression of CXCL10, TNF-α, CCL2, CCL3, IL-8, and IL-6 among 74 volunteers, from a pool of 923, with one (HbAS and HbAC), two (HbSS, HbSC, HbCC) and no (HbAA) copies of the Hb allele variant S and/or C with (+) and without (-) malaria." (PMID 33424841, 2020). "Moreover, TNF-α/IL-10 ratio increased exponentially in malaria-infected donor blood, while in the noninfected donor blood, marginal elevations were recorded." (PMID 33195706, 2020). "Furthermore, defibrotide reduced tumor necrosis factor (TNF)-α expression in lipopolysaccharide (LPS)-stimulated dendritic cells and it attenuated the prothrombinase activity, platelet and complement activation in in vitro malaria models." (PMID 31366975, 2019). "Similarly, plasma TNF-α and TGF-β level of HAT (35.15 and 1379 pg/ml) or malaria (32.22 and 1434 pg/ml), was significantly elevated over healthy controls (24.11 and 534.7 pg/ml), (HAT significance: P = 0.0052 and P = 0.0003 or malaria significance: P = 0.0103 and P = 0.0009) respectively." (PMID 31687034, 2019). "Malaria could affect early T cell polarization by disrupting dendritic cell function, and DCs co-incubated with blood-stage parasites in vitro are shown to polarize naïve T cells toward a TH1-like phenotype that produces IFN-γ and TNFα." (PMID 31156642, 2019). "Additionally, serum levels of IFN- γ and TNF- α were significantly higher in malaria-infected individuals compared to non-infecting individuals and cytokine levels were found to be correlated with recurrent malaria infection." (PMID 34557294, 2019). "Among these mediators, TNF, IL-1β, MCP-1, and IFN-γ have been demonstrated to influence endothelial cell receptors, increasing iRBC cytoadherence and sequestration and promoting localization of activated leucocytes in the brains of infected animals in experimental models of severe malaria." (PMID 31869339, 2019). "Malaria-naïve adults and children from low-transmission regions tend to generate strong pro-inflammatory responses: TH1 cytokines IFN-γ and TNFα, and other pro-inflammatory cytokines such as IL-1β and IL-6, are produced, which may favor generation of TH1-like responses." (PMID 31156642, 2019). "In malaria, IFN-γ has direct antiparasitic action and may act in synergism with TNF-α." (PMID 30126413, 2018). "The development of severe malaria anemia in African children may be a result of a lack of IL-10 production in response to high TNF-α concentrations." (PMID 29970128, 2018). "The anti-TNF properties of artesunate alone evidently do not reduce circulating MV levels in infected mice, presumably because TNF is only one of many agonists present in severe malaria that can stimulate MV production." (PMID 30564748, 2018).
malaria (continued). "Likewise, the role of TNF and IL-10 have been studied in the development of P. falciparum-induced anemia; however, such a role has not been observed in the development of malaria-induced thrombocytopenia." (PMID 30510885, 2018). "In addition to producing type I IFNs, DCs produce a wide range of pro-inflammatory cytokines, including TNF-α, IL-12, and IL-6, and chemokines, such as CXCL1, CXCL2, CCL2, CCL5, CXCL9, and CXCL10 in response to malaria parasites, and play crucial roles in malaria immunity and pathogenesis." (PMID 30619355, 2018). "In addition, acquisition of TNF tolerance has been presumed in the case of malaria-infected mice, in which Plasmodium infection and released TNF did not result in perceivable symptoms of disease." (PMID 29250561, 2017). "With respect to CD4 T cells, recent observations in individuals vaccinated with RTS-S, a recombinant CSP-based vaccine, and in individuals naturally exposed to malaria suggest an important role for CD4 T cell production of TNF, with or without IFN-γ, as a potential immune correlate of protection." (PMID 28871201, 2017). "Not all malaria-infected children with high levels of Th1 proinflammatory cytokines, such as TNF-α, develop severe malaria, suggesting that the cytokine network as a whole, rather than a single cytokine, may contribute in different ways to severe disease." (PMID 28122790, 2017). "IFN-γ, TNF-α, and cytotoxic activity were found to be absent in TIM3+ γδ T cells upon re-stimulation with malaria antigens, and increased frequencies of these cells were associated with reduced risk of clinical malaria." (PMID 28615061, 2017). "A recent RNA-seq study of naïve and malaria-experienced Colombian volunteers who underwent CHMI with P. vivax also found no differential response in the fever-inducing inflammatory cytokines IL-1β, IL-6, IL-8 and TNF between naïve and malaria-experienced individuals at the time of diagnosis." (PMID 27506615, 2016). "Severe malaria patients exhibit high levels of serum pro-inflammatory cytokines (TNF, IL-1β, IL-6, IL-8, IL-12, IFNγ) and chemokines (CCL2, CCL5, CXCL9, CXCL10), and lower levels of regulatory cytokines (IL-10, TGFβ, PGE2) compared to those with mild and asymptomatic malaria." (PMID 27792766, 2016). "We report high plasma levels of proinflammatory cytokines and chemokines (IFNγ, TNF, IL-6, CCL2, CCL3, CCL4, CXCL10) in severe malaria patients compared to baseline uninfected follow-up, which matched that of Py infection in mice in which we could conduct a temporal analysis." (PMID 27792766, 2016). "Elevated levels of circulating tumor necrosis factor (TNF), interleukin-6 (IL-6), IL-12, IL-1β, and IL-10 have been reported to correlate with malaria disease severity and with fatal outcomes; the behaviour of these cytokines in asymptomatic parasitaemia remains unknown." (PMID 24642188, 2014). "Interestingly, PvMSP-119-stimulated PBMCs from malaria patients showed higher TNF response than those recorded in both PSS1-stimulated and non-stimulated PBMCs." (PMID 24041406, 2013). "Anemia in malaria is believed to occur due to hemolysis of parasitized and nonparasitized RBCs, peripheral removal/sequestration of RBCs, and ineffective erythropoiesis (due to high circulating tissue necrotic factor (TNFα))." (PMID 25285308, 2013). "The IL-10 and TNF production capacity and the activation phenotype of monocytes and T cells were compared in samples collected from 332 Ghanaian children with non-overlapping SMA (n = 108), cerebral malaria (CM) (n = 144) or uncomplicated malaria (UM) (n = 80) syndromes." (PMID 22853732, 2012). "We measured plasma levels of soluble UA and inflammatory cytokines and chemokines (IL-6, IL-10, sTNFRII, MCP-1, IL-8, TNFα, IP-10, IFNγ, GM-CSF, IL-1β) in 470 Malian children presenting with uncomplicated malaria (UM), non-cerebral severe malaria (NCSM) or cerebral malaria (CM)." (PMID 23071567, 2012).
malaria (continued). "Thus, even though both TNF-α and IFN-γ are classified as pro-inflammatory cytokines and even though both increase during acute bouts of clinical malaria, TNF-α is a better candidate cytokine than IFN-γ to stimulate HIV production during P. falciparum infection." (PMID 22745697, 2012). "It has been proposed recently that malaria parasites manipulate their host hepatocytes to make them resistant to the apoptosis induced by TNF-α in vivo or in vitro through interference with the NF-kB pathway and consequently allowing them to escape the TNFR1-signaled cytotoxic effect of TNF-α." (PMID 21394207, 2011). "It has been described that pro-inflammatory cytokines like TNF-α have can impact myocardial function via negative-inotropic effects which may play a role in malaria patients." (PMID 21658247, 2011). "Such an evidence demonstrated that during malaria a pathological autoenhancing loop between MMP-9 and TNF is likely, and the inhibition of MMP-9 could be particularly important in order to avoid detrimental inflammatory effects during complicated malaria, CM above all." (PMID 21760809, 2011). "Consistent with this, levels of TNF-α, IL-10 and IL-6 in placental blood (but not peripheral blood) were inversely correlated with peripheral Apo-AI levels in malaria-infected primigravidae (r = −0.385, p = 0.0017, n = 67; r = −0.484, p = 0.0002, n = 62; r = −0.353, p = 0.025, n = 50 respectively)." (PMID 20098675, 2010). "A perhaps surprising finding in our study was the apparent absence of classical macrophage activation in the lung despite the clear presence of malaria parasites: we did not detect iNOS, IL-12p40 nor elevated TNF-α mRNA in lung tissue of Pcc-only or co-infected mice at any time point." (PMID 19951425, 2009). "Five TNF enhancer SNPs and the FCGR2A R131H (G/A) SNP were analyzed for association with severity of P. falciparum malaria in a malaria-endemic and a non-endemic region of India in a case-control study with ethnically-matched controls enrolled from both regions." (PMID 18194515, 2008). "Understanding the role of Tr1 cells, and TNFα expressing CD4+ T cells, in gravidity-dependent antimalarial protection may help efforts towards developing vaccines and other therapeutic interventions to protect pregnant women from the adverse outcomes of malaria in pregnancy." (PMID 37634385, 2023). "Furthermore, the low TGF-β/tumour necrosis factor-α (TNF-α) ratio implies that a lack of TGF-β response in children with severe malaria may result in TNF-α overproduction." (PMID 36288040, 2022). "However, for the malaria group, four distinct correlation patterns were observed; first pattern (CCL4, CCL2, CCL3, IL12 and IL2), second pattern (IL-17A, IL-1β, CCL11, IL4), third pattern (IL5, IL7, IL13), and fourth pattern (IL1RA, CXCL10, TNFα, IL2R, CXCL9, IL6)." (PMID 35811678, 2022). "In addition, DBL3-specific IgG mid pregnancy from pregnant women with non-placental malaria at delivery induced significantly higher IFNγ and TNFα production (IFNγ: p-value = 0.0322, TNFα: p-value = 0.0184) compared to IgG from non-pregnant malaria-naïve healthy individuals." (PMID 33602987, 2021). "However, the function of IL-10 in malaria is still unclear as IL-10 producing CD4+ T cells were involved in dampening severe pathology during Plasmodium infection whereas, it had also been reported to reduce levels of IFN-γ and TNF-α, which helps the parasites to escape the immune response." (PMID 28830553, 2017). "However, the cluster of cytokines—TGF-β, TNF-α, IL-10, and IL-1β—that differentiated CM from other falciparum malaria manifestations in Gondia could not distinguish severe malaria cases in Odisha." (PMID 26602091, 2015). "In addition, we found that children with the fewest prior episodes of malaria were significantly more likely to have malaria-specific production of TNFα without IL-10, and that the absence of this inflammatory cytokine was associated with the phenotype of asymptomatic infection." (PMID 24415936, 2014).
malaria (continued). "In malaria patients with HbS, serum levels of C-X-C motif chemokine ligand 10 (CXCL10), tumor necrosis factor-α (TNF-α), chemokine (C-C motif) ligand 2 (CCL2), interleukin-8 (IL-8), and interleukin-6 (IL-6) are lower compare to malaria patients without HbS." (PMID 40993672, 2025). "In contrast, the correlation between TNF-α and APOA1 levels in the uncomplicated malaria group was not statistically significant (Spearman rho r = 0.098, p = 0.495)." (PMID 40061813, 2025). "We first assessed circulating cytokine (IL-6, IL-10, TNF-α, IFN-3γ) concentrations among healthy participants with- and without asymptomatic malaria and patients with clinical malaria." (PMID 34177883, 2021). "Despite that, in participants with symptomatic malaria, the degree of CCL2 perturbation exhibited two negative correlations, vs. IL-6 and TNF-α." (PMID 34727121, 2021). "Significant correlations were identified for select individual genotypes with and without malaria between CXCL10, TNF-α and IL-6 with Hb, WBC, and RBC." (PMID 33424841, 2020). "In a separate study in Malawian children, those presenting with severe malaria had higher levels of IL-6 and TNF-α than did those presenting with UCM, although severe malaria was not further subcategorized." (PMID 28122790, 2017). "In contrast to TNFα, IL-6, IL-8, IL-15 and MCP-1, eotaxin was not often mentioned in previous malaria studies." (PMID 27168977, 2016). "Plasma TNF-a, RANTES and antibodies to recombinant malarial proteins as well as levels of circulating CD4+ CD25high cells were comparable in malaria patients with or without filarial infections." (PMID 23837823, 2013). "Here we demonstrate that MPs, derived from the plasma of malaria infected mice, but not naive mice, induce potent activation of macrophages in vitro as measured by CD40 up-regulation and TNF production." (PMID 20126448, 2010). "This fact did not, however, alter the increase of malaria-induced IFN-γ and TNF-α as the malaria infection progressed in co-infected mice." (PMID 18656411, 2008). "This study found increased plasma levels of proinflammatory cytokines: TNF‐α, IFN‐ɣ, IL‐1β, IL‐6, and GM‐CSF, and the anti‐inflammatory cytokine IL‐10 in malaria‐infected children than the controls without malaria, and the levels were higher in participants with high parasitemia." (PMID 39240033, 2024). "However, levels of TNF‐α,10 IL‐1β,16 IL‐6,8, 33 IFN‐ɣ,33 IL‐10,11, 33 and GM‐CSF27 were not different when malaria‐infected children were compared to their counterparts without the infection in previous studies." (PMID 39240033, 2024). "Furthermore, we previously showed that different sickle Hb genotypes with or without malaria parasites have different levels of CXCL10, CCL3, IL-8, TNF-α, and IL-6 in the blood." (PMID 37108709, 2023). "In the gene expression analysis, elevated levels of TNF-α and IFN-γ with downregulation of IL-2 and upregulation of TGF-β mRNA levels were observed in patients with severe malaria, but not in patients with uncomplicated malaria." (PMID 35954703, 2022). "The previous study suggested that serum IL-12 levels and other cytokines such as TNF-α, IFN-γ, and CRP levels might not be candidate markers for severe malaria because of the absence in the difference in their levels in higher parasite densities." (PMID 35954703, 2022). "We observed a clear correlation between TNF-α levels and EBV-DNA load in Malaria cases involving P. falciparum (R2 = 0.8915), but not in the P. vivax or mixed Malaria cases (R2 = 0.08050 and R2 = 0.1137, respectively) nor in the healthy controls (R2 = 0.007915)." (PMID 34962938, 2021). "CD4+ T cells are not known to directly kill the malaria parasite but can indirectly exert antiparasite activity through the production of key cytokines such as IFN-γ and TNF, which are essential mediators of the parasite-specific adaptive immune response (reviewed in reference 28)." (PMID 34663097, 2021).
malaria (continued). "Importantly, a large percentage of malaria antigen-specific CD4+ and CD8+ T cells produced both TNF-α and IFN-γ (with or without MIP-1β), with the remainder generating individual cytokines including IL-2." (PMID 30673723, 2019). "Here we found that Malawian children presenting with all forms of malaria had high IL-10-to-TNF-α and IL-10-to-IL-6 ratios, so high levels of TNF-α and IL-6 in CM could not be attributed to a lack of IL-10 response." (PMID 28122790, 2017). "Similar levels of immunogenic MPs were produced in WT and in TNF−/−, IFN-γ−/−, IL-12−/− and RAG-1−/− malaria-infected mice, but were not produced in mice injected with LPS, showing that inflammation is not required for the production of MPs during malaria infection." (PMID 20126448, 2010). "Among both children less than 5 years, and those from 5 to 12 years, TNF‐α (p < .001), IFN‐ɣ (p < .001), IL‐1β (p < .001), IL‐6 (p < .001), GM‐CSF (p < .001), and IL‐10 (p < .001) levels were elevated in the participants with malaria compared with the apparently healthy children without malaria." (PMID 39240033, 2024). "The phenotype of CSP-specific CD4+ T cells that has been associated with vaccine-induced protection against clinical episodes of malaria is TNF-α+, but not IL-2+ or IFN-γ+;56,79 and in part, TNF-α+ CD4+ T cells may also be induced by natural exposure to malaria parasites." (PMID 28934066, 2018). "TNF-α, IFN-γ, IL-1, IL-6, IL-8, and IL-10 have been found in increased levels in patients with severe malaria compared to healthy controls, decreasing in convalescence to control levels, but in these studies the clinical syndromes of severe malaria were not fully described." (PMID 28122790, 2017). "A study in a seasonal malaria transmission area in Kenya found no seasonal differences in the frequency of IFN-γ and IL5 ELISpot responses, but higher frequencies of ELISpot responses to IL10 and TNF during the high transmission season compared to the low transmission season." (PMID 26830334, 2016). "The frequency of SNPs in DDX39B (-22C > G and -348C > T), TNF (-308G > A) and IL6 (-176G > C) were compared between P. vivax-infected study participants who exhibited different clinical outcomes, including asymptomatic infection, mild malaria, complicated malaria, and no infection." (PMID 25038626, 2014). "Importantly, for TNF and IFN-γ the lower P. falciparum infection intensity recorded amongst the co-infected cohort did not flaw the comparison with the malaria patients, as statistically significant differences still distinguished the two groups after parasitaemia stratification." (PMID 24886212, 2014).